PCSK9 (proprotein convertase subtilisin/kexin type 9)
Diseases named in the same sentence as PCSK9 in open-access papers (continued):
Sharing a sentence is not in itself a finding about the gene and the disease.
diabetes (239 papers, 2013 to 2026). "Pharmacotherapy with statins, ezetimibe, proprotein convertase subtilisin/kexin type 9 (PCSK9) inhibitors and bempedoic acid has convincingly been shown to reduce the cardiovascular risk of people with diabetes." (PMID 42162471, 2026). "The reported results further support the important correlation between PCSK9 and CV risk related to diabetes and menopause, thus highlighting its potential role as an additional biomarker of CV risk in post-menopausal diabetic women." (PMID 40144869, 2025). "The FOURIER trial, which studied the PCSK9 inhibitor evolocumab, assessed its efficacy and safety, including the impact on glycemia and the risk of developing diabetes." (PMID 39775321, 2025). "Inclisiran, an siRNA targeting PCSK9, was also evaluated for its effects on glycemia and diabetes risk." (PMID 39775321, 2025). "PCSK9 is primarily produced by the liver and increased circulating PCSK9 appears associated with metabolic disorders including insulin resistance and diabetes." (PMID 39940773, 2025). "Some studies have raised concerns about a potential link between PCSK9 inhibitors and an increased risk of new‐onset diabetes." (PMID 39479289, 2024). "This trend is consistent with a higher diabetes risk in individuals harboring PCSK9 LOF variants with impaired fasting glucose at baseline, despite a reduced risk of CAD." (PMID 39139638, 2024). "Mendelian randomisation studies have found that genetic variants mimicking the effects of PCSK9 inhibitors are associated with an increased risk of diabetes or hyperglycaemia." (PMID 38376536, 2024). "A significant correlation has been found between PCSK9 and glucose metabolism, but studies linking PCSK9 LOF variants to the risk of developing diabetes are conflicting." (PMID 38344397, 2024). "In subgroup analysis of each PCSK9 inhibitor, alirocumab treatment afforded a significant reduction in the risk of diabetes-related adverse events compared to control treatment (RR = 0.9137; 95% CI, 0.845–0.987)." (PMID 36704607, 2023). "The results showed that variants in PCSK9 had a nearly identical effect as statin therapy on the risk of cardiovascular diseases and diabetes per unit decrease in plasma LDL-C level." (PMID 36834701, 2023). "The cholesterol absorption inhibitor ezetimibe and PCSK9 inhibitors have also been shown to lower risk in patients with diabetes." (PMID 36012115, 2022). "Variants in PCSK9 had approximately the same effect as variants in 3-hydroxy-3-methylglutaryl-coenzyme A reductase (HMGCR) on the risk of diabetes per unit decrease in the LDL-C." (PMID 36383291, 2022). "LDL-C lowering alleles at PCSK9 were associated with a higher risk of diabetes, namely, each 1 mmol/L (38.7 mg/dL) genetically predicted reduction in LDL-C led to an odds ratio of 1.19 (95% CI, 1.02–1.38)." (PMID 36383291, 2022). "Given the higher prevalence of diabetes among men and the elderly, the question arises if they also have a greater risk of glucose abnormalities when using PCSK9 inhibitors." (PMID 36506552, 2022). "Currently, it remains controversial regarding the relationships between circulating PCSK9 levels and glucose metabolic parameters, diabetic status and the risk of new onset diabetes, and further clarification is needed." (PMID 35596184, 2022). "A number of Mendelian randomization studies and a meta-analysis have suggested a potential association between PCSK9 inhibition and increased risk of diabetes mellitus." (PMID 35900635, 2022). "The individual risk of the variants was depending on the individual extent of functional loss, with the highest risk of diabetes occurring in the variant with the highest LDL-C lowering (lowest PCSK9 function)." (PMID 36527064, 2022).
diabetes (continued). "Another study in 568,448 subjects (average plasma LDL‐C of 3.41 mmol/L) reported an increase of 0.09 mmol/L in fasting plasma glucose and 29% in the diabetes risk for every 1 mmol/L decrease in plasma LDL‐C attributed to 4 PCSK9 LOF variants." (PMID 33527668, 2021). "Variants in PCSK9 have been associated with an increased risk of diabetes (OR 1.1, 95%CI 1.0, 1.2 for each 10 mg per decilitre decrease in LDL-C)." (PMID 33886544, 2021). "The majority of the results showed that diabetes was significantly associated with increased plasma levels of PCSK9, but there are also contradictory results showing an inverse relationship." (PMID 34380558, 2021). "The use of statins has been linked to increased risk of T2D, but PCSK9 inhibitors have also been implicated in the development of diabetes and further long-term observations are required." (PMID 33801208, 2021). "The effect of anti-PCSK9 in increasing the risk of diabetes, as it markedly lowers LDL-C, was assessed using genetic scores." (PMID 34940565, 2021). "Genetic studies have shown that PCSK9 alleles associated with reduced LDL cholesterol levels increase the risk of developing type 2 diabetes mellitus (T2DM)." (PMID 34380558, 2021). "Genetic variants that mimic the effect of PCSK9 inhibitors had a very similar effect on the risk of cardiovascular events and diabetes." (PMID 34940565, 2021). "Previous genetic studies of PCSK9 inhibition suggested that reduced LDL-C levels by inhibiting PCSK9 activity were significantly associated with a higher incidence of diabetes." (PMID 34712689, 2021). "This is an important finding, as both data from PCSK9 KO mice and data from patients with genetic PCSK9 variants indicated an increased risk of type 2 diabetes mellitus." (PMID 33643060, 2021). "Subsequently, multivariate linear regression analysis indicated that serum Pcsk9, Apob, NT-proBnp and CK levels and diabetes history were positively associated with high SYNTAX scores (all P < 0.05)." (PMID 34044829, 2021). "This study aimed to investigate the susceptibility of 8 polymorphisms in ApoB and PCSK9 genes to diabetic kidney disease (DKD) in Chinese patients with type 2 diabetes mellitus." (PMID 33889589, 2021). "In this study, we determined factors associated with circulating PCSK9 in a group of patients with type 2 diabetes mellitus (DM2)." (PMID 35024053, 2021). "The most striking finding in the current study was the positive association of circulating PCSK9 levels with an increased risk of diabetes only in female subjects with prediabetes." (PMID 33302966, 2020). "The effect of sex on the association between PCSK9 and the development of diabetes needs to be delineated in more detail in future studies." (PMID 33302966, 2020). "More recently, a cohort study found that high circulating PCSK9 is associated with an increased risk of diabetes in individuals after renal transplantation." (PMID 33302966, 2020). "A replication analysis in the Africa America Diabetes Mellitus (AADM) study found the PCSK9 variant to be significantly associated with low LDL-cholesterol levels (Beta = -0.10)." (PMID 32084179, 2020). "Two recent publications on PCSK9 genetic variants with mendelian randomization and meta-analysis reported increased glucose, increased weight, and increased diabetes with this medication." (PMID 30922303, 2019). "In particular, patients with specific loss-of-function PCSK9 mutations or polymorphisms had increased prevalence in pre-diabetes and diabetes as well as higher HOMA-IR index and insulin levels." (PMID 31672148, 2019). "These discrepancies motivate the need for more studies to clarify the relationship between LOF PCSK9 variants and glucose concentrations as biomarkers of diabetes." (PMID 30899674, 2019).
diabetes (continued). "Notwithstanding the increased risk for type 2 diabetes mellitus linked with PCSK9 rs11591147-T, our results indicating minute effects on glycolysis traits are in line with larger studies reporting null effects on fasting glucose for this SNP." (PMID 30524137, 2018). "After adjusting for age, gender, essential hypertension, diabetic mellitus, smoking and lipid profiles, PCSK9 levels remain significantly associated with increased CAD susceptibility (OR = 1.002, 95% CI = 1.001–1.002, P < 0.001)." (PMID 30205809, 2018). "Several studies have suggested that an increase in PCSK9 levels is associated with higher fasting insulin levels in general populations and patients with diabetes." (PMID 29618348, 2018). "We sought to investigate the associations of LDL cholesterol-lowering PCSK9 variants with type 2 diabetes and related biomarkers to gauge the likely effects of PCSK9 inhibitors on diabetes risk." (PMID 27908689, 2017). "The first major genetic polymorphism study of PCSK9 variants and their association with diabetes has suggested that diabetes risk is 15–20% higher in the context of a 1 mmol/l genetically predicted reduction in LDL-cholesterol." (PMID 28025677, 2017). "This is the first large genetic study linking PCSK9 snps to diabetes risk and reports a significant higher risk, albeit modestly so, but with stronger associations with diabetes for genes encoding the molecular targets for ezetimibe." (PMID 27864787, 2016). "This might contribute to the ongoing discussion of PCSK9 inhibitors increasing the risk of diabetes." (PMID 38532495, 2024). "In summary, studies in pathophysiology and genetics indicate that PCSK9 inhibition may modestly elevate the risk of new-onset diabetes." (PMID 39767636, 2024). "PCSK9 and diabetes mellitus are significant predisposing factors regarding LDL-C catabolism." (PMID 38393015, 2024). "A large-scale meta-analysis of genetic association studies has shown that exposure to LDL-C-lowering genetic variants near NPC1L1 and PCSK9 genes is associated with an increased risk of type 2 diabetes, with a 1.19 to 2.42-fold increase in overall diabetes risk per 1 mmol/L decrease in LDL-C." (PMID 39717102, 2024). "Effects of islet autocrine PCSK9 deficiency on islet β cell function and diabetes risk." (PMID 39139638, 2024). "PCSK9 was also reported to be associated with insulin secretion and diabetes mellitus (DM)." (PMID 37012310, 2023). "A recent study showed that the baseline PCSK9 levels were independently associated with the risk of MACEs in stable CAD patients with diabetes mellitus (DM), and the patients with high PCSK9 levels plus DM had an extremely high risk of MACEs compared with those with low PCSK9 levels and non-DM." (PMID 35596184, 2022). "We hypothesize that rs2483205 and rs2495477 polymorphisms may be involved in the development of diabetes by decreasing plasma PCSK9 levels, leading to impaired islet function." (PMID 35733117, 2022). "In the PCSK9 deficiency condition, although the plasma cholesterol level is decreased, cholesterol accumulation in the β-cells increases, leading to β-cell dysfunction and diabetes." (PMID 34380558, 2021). "The reasons for these discrepancies are unclear, but the concentration and duration of PCSK9 deficiency may contribute to the increased risk of diabetes and need to be addressed in the future." (PMID 34380558, 2021). "MR has previously demonstrated the protective effect of cholesterol-lowering drugs on cardiovascular disease risk, but also that inhibition of HMGCR and PCSK9 may have an adverse effect on diabetes risk." (PMID 33886544, 2021). "In view of the common occurrence of diabetes linked life-habits with depression, the evaluation of PCSK9 may thus offer a pathophysiological link, being associated with an insulin resistance marker, predictor of a raised CV risk." (PMID 33143700, 2020).
diabetes (continued). "However, a Mendelian randomization study presented evidence of causality between selected (LOF) PCSK9 variants that are proxies for PCSK9 inhibitors, and increased risk of diabetes." (PMID 30899674, 2019). "Interestingly, the direct relationship between PCSK9 and Lipoprotein (a) observed in the present study is in keeping with the association of low PCSK9 levels with insulin resistance and diabetes." (PMID 31672148, 2019). "Also, variants in other genes associated with lower LDL-C concentrations, such as variants in proprotein convertase subtilisin/kexin type 9 (PCSK9), were also associated with increased risk of diabetes." (PMID 30153257, 2018). "Mendelian randomization studies with genetic variants in PCSK9 have also shown an increased risk of diabetes, and whether PCSK9 mAbs carry a risk of development of diabetes has been a matter of concern." (PMID 29794992, 2018). "Whether lowering of LDL cholesterol by PCSK9 inhibitors results in increased risk of diabetes is currently unknown." (PMID 27908689, 2017). "Indeed, a recent relevant study exploiting genetic data has examined this issue and reported genetic variants in PCSK9 were associated with a 19 % (95 % CI 2 to 38 %) higher risk for diabetes per mmol/l lower LDL-c levels [14••]." (PMID 27864787, 2016). "However, it has been reported that elevated PCSK9 levels may aggravate the vascular consequences and prognosis associated with diabetes." (PMID 40225015, 2025). "A deficiency of autocrine PCSK9 in the islets may impair β-cell function, leading to diabetes." (PMID 39139638, 2024). "In stable CAD patients with diabetes mellitus (DM), the studies found that baseline PCSK9 levels were independently related to the risk of MACEs." (PMID 37765005, 2023). "Whether PCSK9 inhibitors increase the risk of diabetes is also still under debate." (PMID 36142332, 2022). "Evidence from clinical research also demonstrates that elevated PCSK9 is associated with systematic inflammation and platelet activation, while high levels of PCSK9 predict a greater risk of recurrent ischemia, especially for those with diabetes and ongoing inflammation." (PMID 36291690, 2022). "Increasing data including ours have suggested that proprotein convertase subtilisin/kexin type 9 (PCSK9), a novel regulator of cholesterol metabolism, may also play an important role in the development of type 2 diabetes mellitus (T2DM) and is associated with clinical outcomes in diabetic patients." (PMID 33581713, 2021). "They concluded that elevated PCSK9 levels were associated with an increased incidence of T2DM in female individuals with prediabetes (pre-DM)." (PMID 33581713, 2021). "Besides raised PCSK9 levels, an enhanced CV risk, in our cohort, may be consequent to the increased incidence of insulin resistance and diabetes mellitus." (PMID 33143700, 2020). "Clinical trials of PCSK9 inhibitors to assess their effect on cardiovascular outcomes are ongoing, but reliable evidence for a possible association between PCSK9 inhibition and risk of diabetes could take longer to accrue." (PMID 27908689, 2017). "Additionally, the increased risk of progression to diabetes seen with high-intensity statin treatment might also occur with PCSK9 inhibition, possibly resulting from the intracellular accumulation of lipids in insulin-secreting pancreatic beta cells." (PMID 27095708, 2016). "PCSK9 mAb appears to be effective in reducing the risk of MACE by 18% (OR 0.82, 95% CI 0.74–0.90) in subjects with diabetes and dyslipidemia." (PMID 38907775, 2025). "Post hoc analyses of the ORION-9, ORION-10, and ORION-11 trials further showed that inclisiran significantly decreased PCSK9 levels and other atherogenic lipids in patients with diabetes or obesity." (PMID 40076813, 2025).
diabetes (continued). "In the context of diabetic retinopathy (DR), it is interesting to note that PCSK9 levels have been positively co-related in patients with diabetes, increasing in patients with progressing grades of DR compared to controls with no diabetes." (PMID 39623109, 2025). "T1DM: type 1 diabetes mellitus; T2DM: type 2 diabetes mellitus; PCSK9: proprotein convertase subtilisin/kexin type 9; LDL-C: low-density lipoprotein-cholesterol; HDL-C: high-density lipoprotein-cholesterol; Apo-B: apolipoprotein B." (PMID 40264627, 2025). "Elevated circulating PCSK9 has emerged as a potential biomarker for cardiovascular events in patients with type 2 diabetes mellitus (T2DM)." (PMID 41008547, 2025). "Subgroup analyses from the ODYSSEY OUTCOMES, FOURIER, and PROFICIO phase III trials revealed substantial reductions in plasma LDL cholesterol levels among patients with diabetes receiving PCSK9 inhibitors compared to placebo." (PMID 40076813, 2025). "Sex has been identified as a biological determinant of plasma PCSK9 concentrations in patients with diabetes, with variations observed across different age strata." (PMID 41008547, 2025). "Predictors of achieving targets included male gender, cardiac rehabilitation, recent acute coronary syndrome, diabetes, and triple therapy (statin + ezetimibe + PCSK9 inhibitors)." (PMID 39860503, 2025). "In recent years, researchers have begun to explore the role of Proprotein Convertase Subtilisin/Kexin Type 9 (PCSK9) in the development of diabetes with hyperlipidemia." (PMID 39951410, 2025). "PCSK9, as a key predictor, highlights its potential role in the pathogenesis of diabetes with hyperlipidemia and offers new avenues for targeted therapy." (PMID 39951410, 2025). "Recent reports suggest that PCSK9 plays a crucial role in the onset and progression of many aging-related diseases, such as Alzheimer’s disease, cancer, and diabetes." (PMID 40354375, 2025). "Ezetimibe provides an additional 18% LDL-C lowering and a 14% event reduction in mixed-diabetes trials, while PCSK9 inhibitors offer a potent 40–60% LDL-C reduction and an 18% MACE reduction." (PMID 40943477, 2025). "Although the conclusions of related studies have shown significant discrepancies, the role of PCSK9 and its inhibitors in diabetes and the effects of glucose-lowering drugs on PCSK9 have attracted much attention in recent years." (PMID 41008547, 2025). "Among those 1976 subjects actually eligible to PCSK9-i, 1,415 (72%) presented a diabetes with TOD or RF and 1,016 (51%) patients had a documented ASCVD event." (PMID 39173034, 2024). "Elevated levels of circulating PCSK9 have been observed in individuals with diabetes, chronic kidney disease and psoriasis." (PMID 39254080, 2024). "The SPIRE‐1 and SPIRE‐2 trials investigated the PCSK9 inhibitor Bococizumab in a large cohort of 27,438 patients with a history of cardiovascular disease or diabetes." (PMID 39479289, 2024). "In summary, these recently approved drugs targeting PCSK9 (antibodies and siRNA) are highly effective at reducing LDL-C and CV risk and are well tolerated, particularly in those with diabetes." (PMID 38376536, 2024). "A Mendelian randomization study also demonstrated that variants in PCSK9 and HMG-CoA reductase genes were correlated with higher diabetes risk per unit decrease in LDL-C." (PMID 39113067, 2024). "The combination therapy of ezetimibe, a PCSK9 inhibitor, and bempedoic acid reduced the patient's 10-year cardiovascular disease risk from 5.2% to 3.5%, as calculated using the SCORE2-Diabetes system." (PMID 39691317, 2024).